DMD (dystrophin)
Diseases named in the same sentence as DMD in open-access papers (continued):
Sharing a sentence is not in itself a finding about the gene and the disease.
Becker muscular dystrophy (continued). "Becker muscular dystrophy (BMD), according to the Online Mendelian Inheritance in Man (OMIM #300376), is an X-linked recessively inherited disorder caused by a mutation in the dystrophin gene." (PMID 38022137, 2023). "Moreover, a study of the ability of this method to discriminate between DMD and Becker muscular dystrophy (BMD) patients in the context of dystrophin concentrations in the blood is needed." (PMID 35744792, 2022). "Skeletal muscle biopsies from Becker muscular dystrophy patients showed a less decrease in miR-486 expression to DMD, demonstrating that reduced miR-486 is correlated to pathology related to the loss or decrease of a functional dystrophin protein." (PMID 35512829, 2022). "The DMD had different small deletions in patients P60-Myo139 and P75-Myo151, and the same frameshift deletion c.40_41del in DMD in P25-Myo086 and P58-Myo132, all of whom presented a Becker muscular dystrophy phenotype." (PMID 35741838, 2022). "In this work, we present a Becker Muscular Dystrophy patient with elevated creatinine kinase levels, progressive muscle weakness, mild intellectual disability and a muscle biopsy showing dystrophic features and irregular dystrophin labelling." (PMID 35008485, 2021). "In addition, tadalafil was able to alleviate muscle ischemia in eight out of nine patients with Becker muscular dystrophy (BMD), a milder form of muscular dystrophy which is also characterized by dystrophin mutations." (PMID 34360780, 2021). "Becker muscular dystrophy (BMD) is also a result of mutations in the DMD gene that do not completely disrupt the reading frame of the protein and allow for the production of a shorter version of a partially functional dystrophin." (PMID 33917446, 2021). "Milder Becker muscular dystrophy results from reduced size or levels of dystrophin, which acts to protect skeletal and cardiac muscle membranes by force distribution through interactions with filamentous actin and the dystrophin-glycoprotein complex (DGC)." (PMID 33651713, 2021). "DMD deletions that do not disrupt the reading frame give rise instead to internally truncated, yet partially functional, dystrophins, which underlie Becker muscular dystrophy (BMD; MIM #300376)." (PMID 32252479, 2020). "Mutations that conserve the reading frame lead to a shorter dystrophin protein typically lacking part of the central rod domain region and underlie the milder Becker muscular dystrophy (BMD)." (PMID 29641567, 2018). "It has been observed that patients carrying in-frame as opposed to out-of-frame mutations in DMD usually present with a less severe disorder called Becker muscular dystrophy (BMD)." (PMID 30477208, 2018). "Clinical outcome does appear to be correlated to whether frameshift or nonsense-mediated RNA decay occurs, indeed deletions of up to 50% of dystrophin have resulted in Becker muscular dystrophy." (PMID 29367539, 2017). "Interestingly, Becker muscular dystrophy (BMD), which is also due to mutations in the dystrophin gene, results in a less severe phenotype." (PMID 28134780, 2017). "Loss of functional dystrophin expression leads to development of Duchenne (DMD) and Becker muscular dystrophies (BMD) characterized by severe and progressive muscle weakness and wasting due to increased sarcolemma fragility and susceptibility to myofiber injury." (PMID 28899419, 2017). "Interestingly, Becker Muscular Dystrophy (BMD), which is also caused by mutations in the dystrophin gene, results in a much milder phenotype." (PMID 29271929, 2017). "Dystrophin mutations are associated with Duchenne (DMD) and Becker-type muscular dystrophy (BMD)." (PMID 27347491, 2016). "While KCNJ10 and SLC6A3 codify for ion channels and thus their contribution to epileptogenesis is not unexpected, DMD codes for dystrophin, which has been traditionally associated with X-linked Duchenne and Becker muscular dystrophies." (PMID 27984588, 2016).
Becker muscular dystrophy (continued). "In contrast, multiexon skipping of exons 2–7 to generate a Becker muscular dystrophy-like dystrophin transcript was more challenging and could only be induced efficiently with the phosphorodiamidate morpholino oligomer chemistry." (PMID 24643206, 2014). "Dystrophin is absent in DMD or reduced or truncated in the milder variant Becker muscular dystrophy." (PMID 22238670, 2012). "Interestingly, the allelic disease Becker muscular dystrophy (BMD), which results in a much milder phenotype, is mainly caused by mutations maintaining the open reading frame and allowing the production of a partially deleted but functional dystrophin." (PMID 21798085, 2011). "There are also mutations within the dystrophin gene that lead to internal truncations of non-essential regions, such as the internal rod domain that leads to a mild form of the disease called Becker Muscular Dystrophy." (PMID 20502633, 2010). "In addition dystrophin minigenes, isolated from patients affected by Becker Muscular Dystrophy can partially circumvent the problem of dystrophin mRNA large size." (PMID 17712422, 2007). "Therefore, DMDΔ51–52 pigs resemble Becker muscular dystrophy (BMD), which is caused by DMD mutations with an intact reading frame and results in a later onset and a milder disease phenotype compared with DMD, as internally truncated but partially functional dystrophin is still produced." (PMID 41030228, 2025). "When reduced but functional dystrophin is present, it is considered Becker muscular dystrophy (BMD-OMIM #300376), which carries a better prognosis for the patient." (PMID 41179496, 2025). "It is currently unclear whether the addition of miniaturized dystrophin will mitigate disease progression as effectively as the somewhat larger proteins expressed in patients with Becker muscular dystrophy, particularly because some dystrophic changes will have occurred before gene therapy." (PMID 40579547, 2025). "Mutations that maintain the reading frame allow for truncated dystrophin to be produced, resulting in the phenotype of Becker muscular dystrophy (BMD)." (PMID 39056750, 2024). "Becker muscular dystrophy (BMD) is an X-linked disorder due to in-frame mutations in the DMD gene, leading to a less abundant and truncated dystrophin." (PMID 39358550, 2024). "This new genome-edited rat model of Becker muscular dystrophy (BMD) develops progressive heart failure with reduced ejection fraction and confirms the role of dystrophin in the organization of the cardiomyocyte intercalated discs." (PMID 39358550, 2024). "The development of AOs to induce dystrophin exon skipping was informed by the clear genotype–phenotype correlation, with in-frame genomic deletions typically (but not always) associated with the milder form of Becker muscular dystrophy (BMD)." (PMID 38891760, 2024). "Variants in the DMD gene encoding the protein dystrophin lead to the X-linked allelic disorders Duchenne (DMD, MIM 310200) and Becker muscular dystrophy (BMD, MIM 300376)." (PMID 37254189, 2023). "Becker muscular dystrophy (BMD; OMIM: 300376) is also associated with mutations in DMD, but they tend to encode a partially functional DYSTROPHIN protein and so BMD is generally milder than Duchenne, and could also be considered a secondary satellite cell-opathy." (PMID 34740639, 2022). "Becker muscular dystrophy (BMD) is caused by mutations in the DMD‐gene, leading to truncated and reduced levels of the dystrophin protein in muscle." (PMID 35032073, 2022). "Conversely, ORF-preserving mutations within the DMD gene produce a truncated but partially functional protein, leading to the development of variable phenotypes, ranging from an asymptomatic state to Becker muscular dystrophy (BMD) or DMD." (PMID 35095747, 2021). "This allows production of truncated but partly functional dystrophin proteins such as produced in Becker muscular dystrophy (BMD), a milder form of dystrophinopathy." (PMID 33362201, 2020).
Becker muscular dystrophy (continued). "Becker muscular dystrophy (BMD) (MIM #300376) is similar to DMD but has a more benign phenotype due to preservation of the dystrophin reading frame." (PMID 33029525, 2020). "Even if high efficiency of these therapies is achieved in skeletal muscle, the phenotypic outcome in DMD patients may resemble the disease characteristics of Becker muscular dystrophy or X-linked dilated cardiomyopathy (XLCM) due to the reduced expression and/or truncation of dystrophin." (PMID 31443395, 2019). "Duchenne/Becker muscular dystrophy (DMD/BMD) is the most common genetic neuromuscular disease in children, resulting from a defect in the DMD gene located on Xp21.2." (PMID 31661024, 2019). "AONs eventually promote the translation of an internally deleted dystrophin protein, mimicking what occurs in the milder allelic condition Becker muscular dystrophy (BMD)." (PMID 29579078, 2018). "The milder allelic form of the disease, known as Becker Muscular Dystrophy (BMD) is characterized by less severe symptoms, slower disease progression and longer life expectancy due to the production of shorter, partly functional dystrophin." (PMID 30278058, 2018). "ASOs promote the translation of an internally deleted dystrophin protein mimicking what occurs in the milder allelic Becker Muscular Dystrophy (BMD)." (PMID 28379182, 2017). "At variance with DMD, the milder form of the disease, the Becker muscular dystrophy (BMD), is caused by mutations, including long deletions, which do not perturb the open reading frame (ORF) integrity and produce shorter and partially functional dystrophin isoforms." (PMID 26796035, 2016). "Mutations in dystrophin cause Duchennes Muscular Dystrophy (DMD), Becker Muscular Dystrophy (BMD) and X-linked dilated cardiomyopathy (XLCM) in humans." (PMID 22691118, 2012). "Duchenne and Becker muscular dystrophy (DMD and BMD, respectively) are allelic disorders caused by mutations in the DMD gene, which codes for dystrophin." (PMID 17612397, 2007). "Duchenne/Becker Muscular Dystrophy (DMD/BMD) is a progressive neuromuscular condition caused by mutations in the dystrophin gene (DMD/Xp21) resulting in the lack of functional dystrophin protein." (PMID 41595432, 2025). "In the less severe Becker muscular dystrophy (BMD), decreased expression of dystrophin leads to an attenuated form of the disease." (PMID 38671506, 2024). "In a family that included two boys with Becker muscular dystrophy (BMD) due to a DMD deletion of exons 45–47, maternal carrier testing unexpectedly identified biallelic DMD deletions of exons 45–47 and 49–51." (PMID 36424846, 2023). "There is no approved therapy for Becker muscular dystrophy (BMD), a genetic muscle disease caused by in-frame dystrophin deletions." (PMID 37534133, 2023). "Becker muscular dystrophy (BMD) is a mild disease that is caused by dystrophin truncations and not by its absence." (PMID 35629276, 2022). "Although the association of intellectual disability with the dystrophinopathies Duchenne (DMD) and Becker muscular dystrophy (BMD) has been long established, their association with ASD is more recent, and the dystrophin genotype-ASD phenotype correlation is unclear." (PMID 37861890, 2022). "Although there is heterogeneity in patients with Becker muscular dystrophy (BMD), BMD patients with in-frame deletions in the central rod domain of the dystrophin protein often manifest with milder symptoms compared to DMD caused by out-of-frame deletions." (PMID 34016162, 2021). "This is based on the observation that Becker muscular dystrophy (BMD) patients harboring in-frame deletions in this central domain, produce shorter dystrophin proteins and typically have a mild, late onset disease remaining ambulant for most of their life." (PMID 33949649, 2021).
Becker muscular dystrophy (continued). "In contrast, in-frame mutations, such as Becker muscular dystrophy (BMD), do not fully block dystrophin production but rather result in the expression of truncated dystrophin isoforms of varying size and functionality." (PMID 34445659, 2021). "The identification of deletions or duplications in DMD gene causing Becker muscular dystrophy (BMD) was not unexpected, and only confirmed the clinical overlap between BMD and limb-girdle muscular dystrophy." (PMID 30373198, 2018). "Becker Muscular Dystrophy (BMD) is caused by partial absence of dystrophin; this disease is less severe and less common." (PMID 28744411, 2017). "Two forms of dystrophin-deficient muscular dystrophies are DMD and Becker Muscular Dystrophy (BMD)." (PMID 26230713, 2015). "This method was tested by measuring dystrophin in DMD, Becker muscular dystrophy, and healthy muscle samples." (PMID 25244123, 2014). "Therefore we tested whether NT-proBNP can distinguish patients with Duchenne or Becker muscular dystrophy patients and carriers of a dystrophin mutation with a dilated cardiomyopathy from those without." (PMID 23870371, 2013). "A similar condition, Becker muscular dystrophy (BMD), is also caused by mutation of the DMD gene; however, unlike DMD, the reading frame remains intact in BMD patients." (PMID 24403852, 2013). "Whereas DMD is characterized by the absence of functional protein, Becker muscular dystrophy (BMD), which is commonly caused by in-frame deletions of the dystrophin gene, results in the synthesis of a partially functional protein." (PMID 24276316, 2013). "Becker muscular dystrophy (BMD) is a milder form of the disease, characterized by the presence of partially functional truncated forms of the dystrophin protein." (PMID 17712422, 2007). "There are several therapeutic approaches now approved or in clinical trials, including gene therapy or antisense oligonucleotides (ASO) for exon skipping (to restore an internally truncated dystrophin form, converting DMD to the milder Becker muscular dystrophy, BMD)." (PMID 39535998, 2024). "In general, if mutations do not disrupt the open reading frame, a partially functional dystrophin protein, albeit shorter or longer in the middle, will be produced and result in a milder disease called Becker muscular dystrophy (BMD)." (PMID 37324396, 2023). "Dystrophin mutations that do not completely ablate the protein’s expression or do not alter the protein’s structure severely, cause a milder version of the disease called Becker Muscular Dystrophy (BMD)." (PMID 36979809, 2023). "The new dystrophin isoform could potentially alter the severity of disease in DMD patients and allow for symptoms more similar to Becker’s muscular dystrophy." (PMID 38283433, 2023). "Data showed that dystrophin expression in Becker muscular dystrophy and DMD tissues, normalized against the mean of non-dystrophic control tissues (n = 20), was 4–84.5% (mean 32%, n = 20) and 0.4–24.1% (mean 5%, n = 20), respectively." (PMID 34737451, 2022). "Therefore, reliable methods are needed to monitor dystrophin expression and assess the efficacy of new therapies for muscular dystrophies such as DMD and Becker muscular dystrophy (BMD)." (PMID 36539515, 2022). "However, studies in mdx mice and Becker muscular dystrophy patients that expressed a variety of truncated dystrophin proteins indicated that nNOSμ and α-syntrophin could associate with the sarcolemma independently of the two syntrophin binding sites (SBS) in dystrophin’s carboxyl terminus." (PMID 30349485, 2018). "However, evidence from patients with the milder allelic form of the disease, Becker muscular dystrophy (BMD), suggests that dystrophin can be partially functional, even with the presence of an internal deletion, if the “reading frame” is preserved." (PMID 29912990, 2018).
Becker muscular dystrophy (continued). "In the material of 227 families with Becker muscular dystrophy (BMD), we found nine non-consanguineous families with 17 male individuals carrying a rare mutation—a single exon 48 deletion of the dystrophin gene—who were affected with a very mild or subclinical form of BMD." (PMID 28247318, 2017). "Becker muscular dystrophy (BMD) patients with in-frame deletions including exon 51 typically have a milder phenotype and longer life span than DMD patients; however, in these patients, the shortened dystrophin is present from birth." (PMID 26306629, 2015). "Dystrophin mutations are not just responsible for DMD but also cause a spectrum of other X-linked conditions, such as the milder Becker muscular dystrophy (BMD), cardiomyopathies, and mental retardation." (PMID 24302815, 2013). "Interestingly, mutations in the DMD gene that do not disrupt the reading frame and allow production of internally deleted dystrophins are associated with progressive Becker muscular dystrophy (BMD)." (PMID 36911945, 2023). "Even gene correction of dystrophin in the myocardium, which converts DMD to Becker Muscular Dystrophy (BMD, a milder form of the disease) at a later stage of the disease, cannot mitigate the inflammation and fibrosis in cardiac muscle of DMD patients." (PMID 32341395, 2020). "Becker muscular dystrophy (BMD) patients on the other hand still have residual dystrophin expression and therefore might not show the same late-onset progression of CNS symptoms as observed during this mdx mouse study." (PMID 32360405, 2020). "While DMD is characterized by the absence of dystrophin, mutations that result in the retention of a partly functional dystrophin gene product are characteristic for the less severe dystrophinopathy type, called Becker muscular dystrophy (BMD) (incidence: at least 1 in 18,450 male live births)." (PMID 30360568, 2018). "Furthermore, a prominent 5′–3′ non-horizontal representation of DMD transcript levels has been reported to occur in skeletal muscles of mdx mice and in patients with Becker muscular dystrophy, with reduced transcript levels toward the 3′ end." (PMID 27612288, 2016). "Considering these clinical and morphological findings, a diagnosis of Becker muscular dystrophy was initially supposed; however, later IHC analyses and Western blotting with monoclonal antibodies directed against dystrophin (Novocastra, 28 Newcastle Upon Tyne, UK) did not reveal any abnormalities." (PMID 26404900, 2015). "It has also been demonstrated that the muscle-enriched microRNA, miR-486, is significantly decreased in expression in DMD patient muscle biopsies and myoblast cell lines, but not in the milder Becker muscular dystrophy (BMD) in which a partially functional dystrophin protein is produced." (PMID 27547731, 2015). "Becker Muscular Dystrophy (BMD; MIM# 300376) is a mild form of the disease in which internally-truncated dystrophin molecules are produced as result of in-frame deletions or duplications; these incomplete but functional proteins ameliorate the phenotype." (PMID 25761239, 2015). "In Becker muscular dystrophy (BMD), which typically results from in-frame DYSTROPHIN variants resulting in partial dystrophin function, there is also impaired mitophagy (although not as severe as that resulting from the full dystrophin loss of the dystrophin protein in DMD)." (PMID 34357020, 2021). "Becker muscular dystrophy (BMD), in which the reading frame in the DMD gene is not altered, is similar to DMD, but the progression of symptoms is slower and less severe than DMD because BMD patients have truncated but partially functional dystrophin." (PMID 32693782, 2020). "The patient described has a deletion of dystrophin exon 5 that does not compromise recognition of exon 6, and although the deletion does not disrupt the reading frame, his clinical presentation is more severe than would be expected for classical Becker muscular dystrophy." (PMID 26745801, 2016).
Becker muscular dystrophy (continued). "However, mortality rates from included studies were consistent with findings of two important studies on mortality in dystrophin gene-related muscular dystrophy, which did not meet the inclusion criteria for the current review as they also included patients with Becker muscular dystrophy (BMD)." (PMID 34022943, 2021).